CLDN1 (claudin 1)
Diseases named in the same sentence as CLDN1 in open-access papers (continued):
Sharing a sentence is not in itself a finding about the gene and the disease.
tumor (continued). "Claudin-1 showed a trend to elevation in the tumor tissues of C150-treated mice but the change was not statistically significant, whereas the pro-metastasis marker MMP-2 trended to decrease with C150 treatment." (PMID 34976816, 2021). "In conclusion, in this pilot study, we have shown that measurement of EMT markers (E-cadherin, vimentin, claudin-1, and ZEB1) as well tumor-suppressive miR-205 allows for robust retrospective discrimination of localized ESD-resected and regional surgically resected samples." (PMID 32093260, 2020). "The significantly regulated genes identified in both KYSE150 and KYSE410 cells were found to be involved in cell adhesion (PCDH family genes, CLDN1, CNTN1), cell apoptosis (MAPK10/JNK3, PYCARD), tumor suppression (TUSC3, SAMD9L) and immunity regulation (IFNL3)." (PMID 32089740, 2020). "The results indicate that claudin-1 expression is related to better tumor type, negative venous invasion, and negative lymphatic invasion." (PMID 32855635, 2020). "Claudin (CLDN)-1 is the most-studied claudin in cancers and to date, its role as either a tumor promoter or suppressor (or both) is not established." (PMID 31952355, 2020). "Genes other than CLDN1, CLDN3, CLDN4, CLDN7, and ZO1 may also be coordinately regulated by DOCK1 and may contribute to tumor growth, but this remains to be investigated." (PMID 31717460, 2019). "Our analysis showed that there is a significant negative correlation between expression of KLF4 and claudin-1 and N-cadherin between the normal-appearing mucosa and tumor tissues (P < 0.001)." (PMID 32566755, 2019). "Strikingly, we found that the TJ proteins CLDN1 and OCLN showed an abnormal distribution within the tumor tissue, appearing clumpy and aggregated compared to the typical linear pattern lining the cellular membranes observed in the surrounding nontumorous tissue." (PMID 29538454, 2018). "Likewise, we also showed that TNFα up-regulate genes CLDN-1, IL6, and NFκBIA, which have previously been reported to increase OSCC cell proliferation, supporting our increased tumor volume findings." (PMID 30018735, 2018). "CLDN7, rather than CLDN1, showed higher expression in both undifferentiated tumor tissue and the poorly differentiated CNE2 cells, compared with differentiated tissue and the highly differentiated CNE1 cells." (PMID 28055967, 2017). "Finally, to determine the tumor uptake and the ability of the 6 F6 mAb to specifically target CLDN1 in vivo, 125I-labeled 6 F6 was injected in mice with SW480-CLDN1 and SW480 cell xenografts." (PMID 28659146, 2017). "This study demonstrated that CLDN1 could be a new potential therapeutic target in CRC and that CLDN1 targeting with a specific antibody has anti-tumor effects in vivo and in vitro." (PMID 28659146, 2017). "Analysis of claudins in several different tumor entities shows, with perhaps the exception of claudin 1, no clear-cut pattern between claudin expression and tumorigenicity." (PMID 26243458, 2016). "At the invasive front of the same ESCC tumor, negative expressions of both Nm23H1 and CLDN1 were simultaneously observed." (PMID 27376780, 2016). "On the other hand, pomegranate juice and the combination upregulated genes involved in cell adhesion, in particular E-cadherin in PC3 cells, claudin 1 (CLDN1) in MCF7 cells, and intercellular adhesion molecule 1 (ICAM1) and myristoylated alanine-rich protein kinase C (MARCKS) in both tumor models." (PMID 26180600, 2015). "Multivariate Cox regression analysis for RFS identified negative CLDN1 expression to be an independent adverse factor for tumor recurrence and death (HR 5.529, 95% CI 2.664–11.475, P<0.001; HR 3.459, 95% CI 1.555–7.696, P = 0.002)." (PMID 25393310, 2014). "By using cDNA microarray analysis, our previous study revealed that extracellular ATP could regulate the mRNA expression of Snail, E-cadherin, Claudin-1 and IL-8, which play important roles in EMT and tumor progression." (PMID 25486274, 2014).
tumor (continued). "Furthermore, the mRNA and protein levels of tumor/metastasis suppressors BRMS1, Kiss1 and Claudin-1 were decreased in MCF-7-shPG cells relative to MCF-7 cells (bottom)." (PMID 24260116, 2013). "Claudin 1 levels did not correlate with nodal status (p=0.21), tumor grade (p=0.92), nor tumor size (p=1.0)." (PMID 23721519, 2013). "During the real-time PCR reaction, CLDN1 mRNA was detected in 12 out of 13 analyzed tumours and in 12 out of 13 corresponding surrounding nontumourous breast tissue samples." (PMID 15743508, 2005). "Of 39 malignant tumours examined by immunohistochemistry, 36 were negative for CLDN1 or it was present in a scattered distribution among the tumour cells." (PMID 15743508, 2005). "In these cases the results of immunohistochemistry and real-time PCR appeared to correlate; specifically, CLDN1 appeared to be downregulated in tumours as compared with normal breast, whereas CLDN3 was expressed at similar levels in tumours and normal breast." (PMID 15743508, 2005). "In these cases positivity was observed only in cells of apocrine metaplasia, and the neighbouring tumour tissue was negative for CLDN1." (PMID 15743508, 2005). "First, in 36 of the 39 carcinomas examined, invasive tumour cells were either negative for CLDN1 or it was present in a scattered distribution among such tumour cells." (PMID 15743508, 2005). "Furthermore, in vivo studies revealed that the absence of CLDN1 can inhibit tumor occurrence and metastasis, underscoring its potential role in cancer progression." (PMID 38761291, 2024). "First, we examined the distribution of CLDN1 mRNA expression in TNBC tumor versus non-TNBC tumor." (PMID 36291810, 2022). "Tumor samples of Inserm series were predicted in 2 and 4 subtypes molecular classification using a predictor based on nine genes: ADAM19, ETS1, and PDCD1LG2 for C1 and C2; CLDN1, DSC3, and SLC24A3 for C1A and C1B; CHL1, ECM2, and PTPN13 for C2A and C2B subtype prediction." (PMID 32083805, 2020). "Moreover, claudin-1 was related to the better tumor type, negative venous invasion, and negative lymphatic invasion." (PMID 32855635, 2020). "For example, during the process of tumor-mediated angiogenesis, BM recruit healthy endothelial cells from surrounding brain parenchyma, but the vascularization process is disturbed by tumor-induced lack of transmembrane tight junction proteins occludin, claudin-1, and claudin-5." (PMID 28493907, 2017). "Moreover, analysis of CLDN1 expression in primary tumor samples from patients with mCRC allowed the identification of two CRC molecular subclasses (C3 and C5) that could benefit from CLDN1-targeting therapies." (PMID 28659146, 2017). "Moreover, as with claudin 1, the protein expression of claudin 4 was also found not to be related to nodal status, size of the tumors nor tumor grade." (PMID 23721519, 2013). "Thus, the question of whether CLDN1 functions as a tumor promoter or tumor suppressor has not been established in cancers, including OC." (PMID 33828978, 2021). "However, whether the relationship of high expression of claudin-1 with better prognosis is due to its relationship with better tumor type, negative venous invasion, and negative lymphatic invasion is not clear, which needs more studies to confirm it." (PMID 32855635, 2020). "The tumor can show variable expression of cytokeratins, CD34, desmin, SMA, claudin 1, and muscle‐specific actin and is consistently negative for S100 protein, Kit, and GFAP." (PMID 36074249, 2023). "The majority of claudin-1 low TNBC cases were T2 (7/10), M0 (8/10), AWOD (7/10), AEB grade 2 (7/10), tumour size >3 cm (8/10) and had absent DCIS (8/10)." (PMID 37102018, 2023). "IHC analyses revealed that the tumor cells were positive for EMA and CD34 and negative for claudin-1, GLUT1, S100 protein, MUC4, STAT6, SMA, HMB45 and P16." (PMID 34592995, 2021).
tumor (continued). "However, whether the relationship of high expression of claudin-1 with better prognosis is due to its relationship with better tumor type, negative venous invasion, and negative lymphatic invasion is not clear, which needs more randomized controlled trials (RCTs) to confirm the conclusion." (PMID 32855635, 2020). "In summary, the addition of CLDN1 into the viral genome would increase the immunorecognition of NSCLC cells; however, it may also promote tumor metastasis if the amount is not attenuated." (PMID 39309012, 2024). "From the 20 claudin-1 positive TNBC patients who received the NAC, a statistically significant number (p=0.025) of those patients (16/20 in total) failed to achieve pCR evident by residual tumours’ presence." (PMID 37102018, 2023). "Importantly, in CRC patient tumor sections, we observed a negative correlation between KLF4 levels and mesenchymal markers including TWIST, β-catenin, claudin-1, N-cadherin, and vimentin." (PMID 32566755, 2019). "For ICAM1, IGSF4, EHM2, CLDN1 and MUC1, no methylation was detected in 20 sporadic RCC tumours." (PMID 18195710, 2008).
cancer (166 papers, 2005 to 2026). A tumor composed of atypical neoplastic, often pleomorphic cells that invade other tissues. "In various cancers, CLDN1 shows an altered role; its reduced expression has been linked to cancer progression, increased invasiveness, and the development of metastatic characteristics." (PMID 41399659, 2026). "The localization of CLDN1 as a transmembrane protein cause that this chemokine is perfect target for the enhanced drug absorption for preventing infection and treating cancer." (PMID 41399659, 2026). "IHH-4 and TPC-1 papillary thyroid cancer cells transfected with miRNA-129-5p had significantly downregulated expression of claudin-1 and caused cancer cells apoptosis." (PMID 39458944, 2024). "CLDN1 has been implicated in various cancers; changes in its expression levels have substantial effects on cell migration, invasion, and proliferation." (PMID 39457456, 2024). "Among the 27 claudin family members discovered to date, CLDN1 is strongly implicated in cancer progression." (PMID 37318881, 2023). "One study reported that XIST promotes the migration and invasion of PTC cells by sponging miR-101-3p, which, in turn, targets the CLDN1 gene that codes for claudin-1, a tight junction protein associated with cancer cell migration and invasion." (PMID 35804851, 2022). "The upregulated claudin-1 expression can inhibit the goblet cell differentiation and promote colitis-associated cancer in a Notch-dependent manner." (PMID 33807544, 2021). "In some cancers, CLDN-1 has the opposite role where the decreased expression of CLDN-1 is associated with cancer progression, invasion and development of the metastatic phenotype." (PMID 31952355, 2020). "The association of CLDN-1 with patient survival or recurrence in many cancers suggests its importance as a prognostic marker and as a potential therapeutic target." (PMID 31952355, 2020). "It has been reported that polymorphisms in claudin 1 (CLDN1) are associated with risk of several cancers." (PMID 30910845, 2019). "Though researches about polymorphisms in CLDN1 are rare, protein CLDN1 has been widely investigated in cancers." (PMID 30910845, 2019). "Conversely, in esophageal, prostate and lung cancer loss of claudin 1 correlates with cancer progression, invasion, metastasis, and shorter disease-free survival." (PMID 23844228, 2013). "Altered expression of several claudin proteins, in particular claudin-1, -3, -4 and -7, has been linked to the development of various cancers." (PMID 24009024, 2013). "Claudin-1 is a membrane protein of tight junctions, and is associated with the development of various cancers." (PMID 20937153, 2010). "The molecular mechanisms underlying CLDN1-mediated cancer chemoresistance are diverse and include its interaction with EPHA2 kinase, which promotes stemness, the upregulation of Unc-51-like autophagy activating kinase 1 (ULK1) phosphorylation, and significant alterations in metabolic pathways." (PMID 40943068, 2025). "The loss of claudin-1 and claudin-4 characterized more aggressive cancers." (PMID 39458944, 2024). "Notably, the overexpression of certain claudins like claudin-2 and claudin-4 has been linked with increased malignancy and poor patient outcomes, while others such as claudin-1 show variable associations depending on the cancer subtype." (PMID 39364319, 2024). "Furthermore, we utilized expression data from The Cancer Genome Atlas (TCGA) to investigate the association between CLDN-1 expression and overall survival (OS) in different cancer types." (PMID 31952355, 2020). "The significant up regulation of these molecules in response to claudin 1 knockdown suggests that claudin 1 may be a regulator of genes associated with cancer progression and metastasis." (PMID 23721519, 2013).
cancer (continued). "Over-expression of CLDN1 has been associated with epithelial–mesenchymal transition, increased invasiveness, and metastatic behavior, as well as modulation of epithelial barrier permeability, suggesting a role in drug delivery and treatment efficacy—especially in ROS-based cancer therapies." (PMID 40426863, 2025). "Further research is needed to elucidate the precise regulatory mechanisms involving Cldn1 and AKRs in different cancer types and investigate potential therapeutic strategies targeting this pathway." (PMID 40361399, 2025). "Because the AKR superfamily is involved in anticancer drug resistance in cancer cells, the viability of cancer cells was assessed after exposure to etoposide, doxorubicin, and daunorubicin to clarify the effect of Cldn1 expression on drug resistance." (PMID 40361399, 2025). "This dual role varies depending on specific cellular processes, the expression levels of Cldn1, and the cancer type." (PMID 40361399, 2025). "Proteome analysis revealed a significant downregulation of these proteins in Cldn1-KO cells, and subsequent functional assays demonstrated that this downregulation corresponded to reduced cancer cell proliferation, invasion, and drug resistance." (PMID 40361399, 2025). "In half of the cases, cancer cells with high Cldn1 expression (intensity score 3-2) were less differentiated than those with low Cldn1 expression (intensity score 1-0) in the same tissue." (PMID 40361399, 2025). "A study on LUAD39 demonstrated that the overexpression of CLDN1 can block the malignant progression of cancer cells." (PMID 41461671, 2025). "Conversely, CLDN1 and CLDN12, which are associated with cancer invasion and progression, were significantly reduced by all three antibiotics 17,22,24." (PMID 40847193, 2025). "Chronic inflammation is a key driver of colorectal carcinogenesis, and CLDN1 has emerged as an important link between inflammation and cancer in the colon." (PMID 40687428, 2025). "Low claudin-1 levels in particular play a role in the development of highly metastatic cancer cells and dedifferentiation." (PMID 41516217, 2025). "CLDN1, a vital component of tight junction complexes, functions as an inhibitor of cancer invasion by preserving epithelial barrier integrity and regulating cell permeability." (PMID 41249135, 2025). "Mechanistically, long non-coding RNA X-inactive specific transcript (lncRNA XIST) bound to and downregulated miRNA-101-3p, promoting cancer cell migration and increasing claudin-1 expression." (PMID 39458944, 2024). "In oral squamous cell cancer, CLDN1 has been shown to increase cancer cell invasion through the activation of matrix metalloproteinases." (PMID 38540693, 2024). "On the other hand, claudin-1 upregulation exhibits potential anti-metastatic and anti-cancer effects in ATC (FSTL1) and FTC (dexamethasone)." (PMID 39458944, 2024). "Our results indicate that ANXA2 activates the Akt/mTOR signaling pathway and EMT in ESCC, thereby enhancing cancer invasion and metastasis through the regulation of β-catenin, Snail, and Claudin-1 proteins." (PMID 38658569, 2024). "The neutralizing efficacy of 6F6 was assessed in vitro using colony formation assays involving multiple CLDN1 overexpressing cancer models (pancreatic: BXPC3, PANC-1; ovarian: SKOV-3, IGROV1; hepatocellular: HuH-7) as well as a xenograft model of CRC." (PMID 38371623, 2024). "Other claudin family members besides CLDN1, CLDN3, CLDN4, CLDN6 and CLDN18.2 have also been implicated in various stages of cancer progression, including metastasis." (PMID 38371623, 2024). "Meanwhile, its stimulatory effect on the synthesis of the TJ protein claudin 1 (CLDN1) has been demonstrated in cancer cells." (PMID 39469627, 2024). "Cancer cells contain dysregulated levels of CLDN-1, which trigger cancer cell invasion, aggressiveness, and resistance." (PMID 39003454, 2024).